LGALS9 (galectin 9)
Diseases named in the same sentence as LGALS9 in open-access papers (continued):
Sharing a sentence is not in itself a finding about the gene and the disease.
colorectal cancer (25 papers, 2017 to 2025). A primary or metastatic malignant neoplasm that affects the colon or rectum. "Among the upregulated target genes, we highlighted six that are closely linked to colorectal cancer: LGALS9, GLUT1, IGFBP3, CDK4, DUSP1, and HIF1A." (PMID 41411347, 2025). "In this study, we investigated the expression of TIM-3 and Galectin-9 (Gal-9) in colorectal cancer (CRC) and their associations with oncogenic mutations, MSI status, cytokine profiles, and transcriptional data." (PMID 40724985, 2025). "Furthermore, several genes included in this list have previously been linked to colorectal cancer (i.e. Id1, Lgals9, Stat2, and Dab2)." (PMID 27129739, 2017). "LGALS9 (galectin‐9), a ligand for ICP receptors, has been associated with positive prognosis in colorectal cancer (CC) patients." (PMID 40747615, 2025). "LGALS9, or galectin‐9, serves as a ligand for ICP receptors, and its elevated expression has been associated with a positive prognosis in individuals with colorectal cancer." (PMID 40747615, 2025). "The highest levels of galectin-9 were detected in hematological (except for K562 cells) and colorectal cancer cells." (PMID 31354733, 2019). "We found that pharmacologically induced mitochondrial dysfunction leads to a reduced galectin-9 expression/exocytosis in human colorectal cancer cells and re-distribution of this protein (the effect described for various cellular proteins) into mitochondria." (PMID 31024310, 2019). "Moreover, AP-1 signaling also amplifies TGF-β1 production, which induces galectin-9 expression in colorectal cancer cells." (PMID 41031085, 2025). "In addition, galectin-9 inhibits cell proliferation of colorectal cancer cell lines in vitro and in vivo, and its mechanism is reported to be the induction of apoptosis via miRNA alteration." (PMID 37047155, 2023). "Thus, galectin-9 may be a new target for immunotherapy of colorectal cancer." (PMID 37047155, 2023). "In colorectal cancer, a key role in immune regulation is played by both TIM-3 and its three ligands—galectin 9 (Gal9), HMGB1, and CEACAM1." (PMID 37567938, 2023). "However, the immunomodulatory effect of galectin-9 in colorectal cancer (CRC) remains unclear." (PMID 36527024, 2022). "In particular, high amounts of galectin-9 are secreted by AML and colorectal cancer cells." (PMID 33295886, 2020). "Our study further demonstrated that TGF-β induces galectin-9 expression in human AML, breast and colorectal cancer as well as embryonic cells but not in the studied healthy (non-malignant) human cells." (PMID 33295886, 2020).
cervical carcinoma (23 papers, 2015 to 2025). A carcinoma arising from either the exocervical squamous epithelium or the endocervical glandular epithelium. "Conversely, hypomethylation of HAVCR2 and LGALS9 promoters, encoding the immunosuppressive molecules Tim-3 and galectin-9, increases their expression in cervical cancer cells, fostering an immunosuppressive TIME and correlating with poorer overall survival." (PMID 41029427, 2025). "EZH2-H3K27me3/DNMT3A-DNA methylation regulates the expression of Tim-3 and galectin-9 in HPV18-associated cervical cancer." (PMID 36766706, 2023). "Overexpression SUV39H1 also associated with increased methylation level of HAVCR2 and LGALS9 which in turn caused Tim-3 and galectin-9 expression decreased in cervical cancer." (PMID 32699524, 2020). "The underlying molecular mechanism of SUV39H1-DNMT3A-Tim-3/galectin-9 regulation was elucidated using cervical cancer cell lines containing siRNA or/and over-expression system." (PMID 32699524, 2020). "Among them, only high expression of LGALS9 was related to a favourable prognosis in patients of cervical cancer (P=0.0072)." (PMID 35924232, 2022). "In this study, the lower expression of LGALS9 was related to the poor prognosis of cervical cancer patients in our prognostic OS model." (PMID 35924232, 2022). "HAVCR2 and LGALS9 promoter regions in cervical cancer tissues displayed hypermethylation status in normal cervical tissues, possibly leading to the inhibition of transcriptional activity of genes in normal cervical tissues." (PMID 32699524, 2020). "In present study, we identified an important role of histone and DNA methylation marks in regulating costimulatory factors Tim-3 and galectin-9 expression in cervical cancer." (PMID 32699524, 2020). "Immunohistochemistry results revealed that both Tim-3 and galectin-9 expressed in tumor cells of cervical cancer tissues, and galectin-9 also showed evident staining in peritumoral inflammatory infiltrate of cervical cancer tissues." (PMID 32699524, 2020). "SUV39H1 targeted DNMT3A by increasing the level of H3K9me3 at the DNMT3A promoter region so that repressed Tim-3 and galectin-9 expression by DNA methylation in cervical cancer." (PMID 32699524, 2020). "In summary, the present study highlights the role of SUV39H1 and DNMT3A in the DNA methylation regulation of Tim-3 and galectin-9 in cervical cancer." (PMID 32699524, 2020). "Tim-3 and galectin-9 are overexpressed in cervical cancer tissues, this biological effect is mediated through the aberrant epigenetic of Tim-3 and galectin-9, which is facilitated by the recruitment of DNMT3A to their promoter regions." (PMID 32699524, 2020). "Knocked-down DNMT3A in cervical cancer cells caused a decreasing of HAVCR2 and LGALS9 methylation level, accompanied by the expression of Tim-3 and galectin-9 elevated." (PMID 32699524, 2020). "The methylation status of HAVCR2 and LGALS9 were detected by MS-PCR in cervical cancer tissues and cell lines." (PMID 32699524, 2020). "The results indicated that the expression levels of HAVCR2 and LGALS9 were all higher in cervical cancer than in normal cervical samples." (PMID 32699524, 2020). "In this review, we mainly focus on the role of galectins, especially galectin-1, galectin-3, galectin-7, and galectin-9 in cervical cancer, and provide theoretical basis for potential targeted treatment of cervical cancer." (PMID 29854732, 2018). "In cervical cancer, a correlation with high differentiation grade has been described for galectin-9 expression, in agreement with the trend toward improved prognosis described in our study." (PMID 26066796, 2015). "Galectin-9, which is encoded by LGALS9, is evidently detected in normal epithelium and endocervical glands but not in cervical intraepithelial neoplasia and cervical squamous cell carcinoma, which indicates that decreased Galectin-9 is a biomarker for the malignant potential of cervical cancer." (PMID 36199574, 2022).
cervical carcinoma (continued). "Histone acetylation of LGALS9 reduces deterioration in cervical cancer." (PMID 36199574, 2022). "The epigenetic-regulation mechanism of the costimulatory factors Tim-3 and galectin-9 in cervical cancer remains unknown." (PMID 32699524, 2020). "After have been determining the baseline levels of DNA methylation on HAVCR2 and LGALS9 promoter regions among cervical cancer cell line, evaluation whether SUV39H1 mediated DNA methylation through DNMT3A is required for HAVCR2 and LGALS9 transcription." (PMID 32699524, 2020). "The epigenetic regulation caused elevated expression of costimulatory factors Tim-3 and galectin-9 in cancer cells, and the abnormal secreted Tim-3 and galectin-9 by tumor cells lead to tumor microenvironment immune imbalance, thereby promoting the development of cervical cancer." (PMID 32699524, 2020). "Our previous study revealed that EZH2-H3K27me3-DNMT3A mediates the epigenetic regulation of the negative stimulatory molecules, Tim-3 and galectin-9 in cervical cancer which is associated with HPV18 infection." (PMID 32699524, 2020). "Here, we identified a novel function of SUV39H1 regulates DNMT3A expression through elevating H3K9me3 level at the DNMT3A promoter region, which could mediate Tim-3 and galectin-9 expression through DNA methylation in cervical cancer." (PMID 32699524, 2020). "Information about galectin-3 and galectin-9 expression in cervical cancer is limited." (PMID 26066796, 2015). "Hence HAVCR2 has a positive correlation with LGALS9 in cervical cancer." (PMID 32699524, 2020). "The upregulated ligand receptor pairs in the cervical cancer group were SPP1 − CD44, FN1 − SDC4, FN1 − SDC1, FN1 − CD44, CD99 − CD99, and the downregulated ligand receptor pairs were PPIA – BSG, LGALS9 − P4HB, LGALS9 − CD44." (PMID 41384115, 2025). "Tim-3 and galectin-9 are overexpressed in cervical cancer cases, which is mediated through the hypomethylation of HAVCR2 and LGALS9 because of the lesser expression and recruitment of DNMT3A to their promoter regions." (PMID 36766706, 2023). "We observed that CD274, CEACAM1, LGALS9, PVR and TNFRSF14 were significantly different (P < 0.05) between two groups, providing a novel insight into immunotherapy for cervical carcinoma patients." (PMID 34789197, 2021). "DNMT3A involved in the induction of genes expression by directly binding to the HAVCR2 and LGALS9 promoter regions, suggested that DNMT3A participate in the epigenetic regulation of HAVCR2 and LGALS9 in cervical cancer." (PMID 32699524, 2020). "After multivariate Cox regression analysis, eight genes were identified as key predictors of HLA-G-driven DEGs in the prognostic risk model for predicting the overall survival of patients with cervical cancer, including CD46, LGALS9, PGM1, SPRY4, CACNB3, PLIN2, MSMO1, and DAGLB." (PMID 35924232, 2022). "Immunotherapy targeting the PD-1/PD-L1 has been successful in advanced cervical cancer, but the potential clinical value of other checkpoint molecules remains unknown, such as TIM-3/LGALS9 or HLA-G/ILT2." (PMID 35924232, 2022).
leukemia (23 papers, 2016 to 2025). A malignant (clonal) hematologic disorder, involving hematopoietic stem cells and characterized by the presence of primitive or atypical myeloid or lymphoid cells in the bone marrow and the blood. "In accordance, anti-galectin-9 treatment of TCL1 AT mice diminished PD1+ TIM3+ T cells along with a reduction in leukemia development." (PMID 40775219, 2025). "By a weekly assessment of CLL cell counts in the blood of the mice, a deceleration of leukemia development was observed by anti-galectin-9 compared to isotype control treatment." (PMID 40775219, 2025). "This activity was dependent on CD8+ T cells, which is in line with our observation of an enhanced CD8+ effector function in anti-galectin-9 treated mice with TCL1 leukemia." (PMID 40775219, 2025). "The pro-apoptotic function of galectin-9 has been described in ovarian cancer, leukemia, and myeloma cell culture models (148–, 150)." (PMID 36873388, 2023). "Galectin-9 inhibited the growth of leukemia and myeloma cancer cells through activating transcription factor-ATF-Noxa, JNK, P38 mitogen-activated protein kinase (MAPK) and caspase-3 pathways." (PMID 36873388, 2023). "In order to assess if Tim-3 is complexed to galectin-9 as in leukemia cells, we performed detection of the Tim-3-galectin-9 complex in tissue homogenates as outlined in the Materials and Methods." (PMID 31354733, 2019). "Given the strong induction of GAL-9 in ACM-exposed human B-ALL cell lines, we next mined publicly available databases to examine the expression levels of LGALS9 (the gene encoding GAL-9) and HAVCR2 (the gene encoding TIM-3) in leukemia cells from patients at diagnosis and relapse." (PMID 35241678, 2022). "The expression of galectin-9 may have played an additional role in the survival of residual leukemia clones early after NK cell infusion when its receptor TIM3 was more highly expressed in the infused CIML NK cell product." (PMID 35349491, 2022). "Galectin-9 produced by the LSCs will bind and stimulate TIM-3-expressing AML cells including LSCs (autocrine effect), supporting their survival or leukemia progression." (PMID 27506934, 2016). "Galectin-9, a ligand for TIM-3, showed elevated levels in the serum of patients with leukemia." (PMID 41051510, 2025). "We observed an exuberant expression of CD122, Galectin-9, and PD-L1 in HL60 cells (gray bars), and found that AKT inhibition primarily decreased the surface expression of these immune checkpoint molecules in leukemia cells (black bars)." (PMID 37341216, 2023). "Besides its expression on immune cells, TIM-3 has been found in AML leukemia stem cells but not in their normal counterparts, and increased levels of Galectin- 9, a TIM-3 ligand, were found in AML patients’ serum." (PMID 38812504, 2024).
lung carcinoma (23 papers, 2014 to 2025). "In our study, we have analyzed galectin-1, galectin-3, and galectin-9, as these are among the most extensively studied galectins in the context of lung cancer." (PMID 38539500, 2024). "In lung cancer, the accumulation of Tim-3-expressing lymphoid cells and galectin-9-expressing monocytic myeloid-derived suppressor cells positively correlates with resistance to anti-PD1 immunotherapy." (PMID 34572756, 2021). "High levels of exosomal Tim-3 and galectin 9 (also known as LGALS9) in plasma exosomes from patients with lung cancer were positively correlated with tumor size, advanced stage, lymph node metastasis, and distant metastasis." (PMID 34511114, 2021). "Of the tandem-repeat galectins, galectin-8 showed no statistically significant change in these cancer types, but galectin-9 was increased in colon and lung cancer." (PMID 34638303, 2021). "In agreement with these outcomes, a recent report identified stromal galectin-9 as a favorable prognostic biomarker in lung cancer." (PMID 35145510, 2021). "Possibly, galectin-9 can act as a chemoattractant for lung cancer cells, similar as described for eosinophils or endothelial cells." (PMID 25259711, 2014). "All these findings show that galectin-1, galectin-3, and galectin-8 are the most abundantly expressed galectins while the expression of galectin-4, galectin-7, and galectin-9 is relatively low, both in tumor tissues and in different lung cancer cell lines." (PMID 25259711, 2014). "In contrast, galectin-9 was elevated in colon and lung cancer patients." (PMID 34638303, 2021). "There was no change in the serum levels of galectin-9 in the serum of the studied patients with stage II or III lung cancer, but galectin-9 was found to be elevated in stages I and IV (p = 0.0030, p = 0.0179, respectively)." (PMID 34638303, 2021). "Thus, exosomal Tim-3, LGALS9, and GAS5 may be ideal noninvasive serum markers to identify patients with early and advanced lung cancer, or even therapeutic targets." (PMID 34511114, 2021). "Finally, galectin-9 on tumor-infiltrating lymphocytes (TIL) in NSCLC has been shown to correlate with T cell immunoglobin and mucin domain containing protein 3 (TIM-3,) as well as the NSCLC drug targets PD-1 and PD-L1 upregulating IFNβ and γ to decrease lung cancer apoptosis." (PMID 38539500, 2024).
nasopharyngeal carcinoma (23 papers, 2006 to 2025). A carcinoma arising from the nasopharyngeal epithelium. "For instance, TDEVs from Epstein-Barr virus (EBV)-associated nasopharyngeal carcinoma (NPC) carry Galectin-9 and induce T cell anergy and death through its binding to the receptor TIM3." (PMID 33260499, 2020). "Reciprocally, there is evidence of excessive galectin-9 production in two human diseases associated with oncogenic viruses : nasopharyngeal carcinomas (NPC) associated with the Epstein-Barr virus (EBV) and chronic infection by the hepatitis C virus (HCV)." (PMID 22805533, 2012). "Excessive production of galectin-9 has been reported in two types of human virus-associated diseases chronic hepatitis C and nasopharyngeal carcinoma associated to the Epstein-Barr virus." (PMID 22805533, 2012). "Secreted galectin-9 has also been implicated in direct Th1 immunosupression by nasopharyngeal cancer cells." (PMID 20209097, 2010). "In a viral study, mammalian galectin-9 was identified as a novel binding partner of Epstein-Barr virus latent membrane protein 1 (LMP1) from nasopharyngeal carcinomas." (PMID 36032131, 2022). "The role of galectin-9 in the regulation of the immune response in the tumor microenvironment has been investigated further in patients with recurrent nasopharyngeal carcinoma." (PMID 29389859, 2018). "Using 1G3 to analyse clinical specimens, we have confirmed that galectin-9 is abundant in two types of human tissues infected by oncogenic viruses, nasopharyngeal carcinoma and liver chronically infected by HCV or HBV." (PMID 22805533, 2012). "Previous studies have demonstrated that Epstein-Barr virus-infected nasopharyngeal carcinoma cells (NPCs) release exosomes containing high amounts of galectin-9, which is able to induce TIM-3-expressing Th1 cell apoptosis and subsequently helps the tumor escape immune recognition." (PMID 29389859, 2018). "Galectin-9 was detected in malignant cells from all nasopharyngeal carcinoma specimens." (PMID 22805533, 2012). "Using 1G3, we could confirm the intense and constant expression of galectin-9 by Epstein-Barr virus positive malignant cells from nasopharyngeal carcinomas." (PMID 22805533, 2012). "Additionally, Epstein-Barr Virus- (EBV-) infected nasopharyngeal carcinoma (NPC) was shown to release exosomes containing high amounts of galectin-9, which induces apoptosis of mature Th1 lymphocytes when interacting with the membrane receptor Tim-3." (PMID 22190973, 2011). "TDEs from nasopharyngeal carcinoma (NPC) have also been found to contain galectin-9, a ligand for Tim-3, which induces apoptosis in mature Th1 and CD4+ T cells, further dampening T cell function." (PMID 40693234, 2025). "In this study, we focused on galectin 9 (G9), an inhibitory ligand that we observed to be predominately positioned on the plasma membrane and readily interacts with CD8 + CTL in the TME of nasopharyngeal carcinoma (NPC)." (PMID 39910335, 2025). "Notably, exosomes derived from nasopharyngeal carcinoma (NPC) cells harbour galectin-9, which, upon circulation in the TME and bloodstream, binds to TIM-3 on Th1 cells, eliciting an immunosuppressive response." (PMID 40994140, 2025). "Furthermore, exosomes from nasopharyngeal carcinoma (NPC) patient-derived sera and NPC cells express galectin-9, which is a ligand of the TIM-3 receptor." (PMID 34831378, 2021).